OR4L1 (olfactory receptor family 4 subfamily L member 1)
Description:
Odorant receptor.
Synonyms: OR4L2P; OR14-28
Tractability: Antibody: its Gene Ontology location is reachable by antibodies, with high confidence; UniProt places it where antibodies can reach, with medium confidence; UniProt predicts a signal peptide or a membrane-spanning region.
Gene: Protein-coding gene on chromosome 14 (20,060,045 to 20,060,983, forward strand). Ensembl gene ENSG00000176246.
Subcellular location: Cell membrane
Pathways (Reactome):
Sensory Perception: Expression and translocation of olfactory receptors; Olfactory Signaling Pathway
Gene Ontology:
Molecular function: olfactory receptor activity; G protein-coupled receptor activity
Biological process: detection of chemical stimulus involved in sensory perception of smell; G protein-coupled receptor signaling pathway
Cellular component: plasma membrane; membrane
Genetic constraint (gnomAD): Missense variants: 386 observed, 321.35 expected, observed/expected ratio (o/e) 1.2, 90% interval 1.1 to 1.31. Synonymous variants: 135 observed, 117.32 expected, observed/expected ratio (o/e) 1.15, 90% interval 1 to 1.33.
Homologues: Orthologues: rabbit OR4L1 (83% identical), dog OR4L1 (80% identical), guinea pig OR4L1 (80% identical), mouse Or4l1 (79% identical), rat Or4l1 (79% identical), mouse Or4l15 (78% identical). Paralogues in human: OR4K13 (59% identical), OR4K15 (58% identical), OR4K14 (58% identical), OR4K17 (56% identical), OR4F4 (55% identical), OR4F5 (55% identical), OR4K2 (54% identical), OR4F17 (54% identical), OR4K1 (54% identical), OR4K5 (54% identical), OR4F6 (53% identical), OR4F15 (51% identical), and 116 more.
Diseases named in the same sentence as OR4L1 in open-access papers:
OR4L1 is named in the same sentence as 3 diseases in open-access papers, as found by Europe PMC text mining. Sharing a sentence is not in itself a finding about the gene and the disease. The quoted sentences say what the papers report.
Anxiety (1 paper, 2025). Intense feelings of nervousness, tension, or panic often arise in response to interpersonal stresses. "The olfactory receptor genes OR4L1 and OR7H2P are linked to sensory pathways associated with anxiety traits, while ATXN1 (6p22.3) connects cognitive and physical genetic risks." (PMID 40125487, 2025). "Recent GWAS have also identified seven significant genetic loci—RNU6–168P, MAT2B, DKK2, DIP2C, COL22A1, OR4L1, and ATXN1—that influence anxiety traits in Caesarean-born offspring." (PMID 40125487, 2025).
anxiety disorder (1 paper, 2025). A category of psychiatric disorders which are characterized by anxious feelings or fear often accompanied by physical symptoms associated with anxiety. "OR4L1, linked to olfactory functions regarding emotions, has yet to establish direct connections to anxiety disorders." (PMID 40125487, 2025).
tumor (1 paper, 2020). "Furthermore, there were six genes (EGR1, MUC20, MUC3A, NBPF19, NOL4L, and OR4L1) that were simultaneously mutated in the tumor tissues and junction tissues." (PMID 33133167, 2020).